MDM2 (MDM2 proto-oncogene)
Diseases named in the same sentence as MDM2 in open-access papers (continued):
Sharing a sentence is not in itself a finding about the gene and the disease.
cancer (continued). "MDM2 inhibitors have been extensively developed as candidate cancer therapeutics and are generally considered highly specific in vivo." (PMID 40044657, 2025). "Clinical studies have identified MDM2 amplification and overexpression in various cancers, including PV, where MDM2 levels are notably higher in PV patients compared to healthy individuals." (PMID 41144126, 2025). "This disruption aligned with MDM2’s role in regulating redox homeostasis and highlighted the therapeutic potential of targeting this pathway to induce oxidative stress in cancer cells." (PMID 40046748, 2025). "Through binding to enhancer of zeste homolog 2 (EZH2), a core subunit of PRC2, MDM2 supports the trimethylation of histone H3 on lysine 27 (H3K27me3) in stem cells and cancer cell lines." (PMID 40911795, 2025). "We suggest that the MDM2-siRNA complex should be taken up by cancer cells in the peritoneal cavity, suppress MDM2-mRNA expression, and induce cancer-cell apoptosis in vivo." (PMID 41009451, 2025). "Targeting MDM2 as a therapeutic strategy for cancers has been extensively studied, and several Phase 3 clinical trials are currently underway." (PMID 39857959, 2025). "Beyond the recurrent amplification of CCND1, CCND2, CDK4, MDM2, and MYCL1, chromothriptic chromosomes were associated with the amplification or loss of other well-established cancer genes." (PMID 39185963, 2025).
cancer (continued). "The activity of these MDM isoforms underscores the complex, isoform-specific role(s) of MDM2 gene products in cancer development and progression." (PMID 39960347, 2025). "MDM2 inhibitors have shown assurance of therapeutic approach in cancer, as several potent and selective compounds have been developed in the recent years." (PMID 40251828, 2025). "Recently, the phase 1 study of the dual MDM2/MDMX inhibitor ALRN-6924 in pediatric cancer demonstrated safety, tolerability, and promising antitumor activity in relapsed or refractory solid tumors and acute lymphoblastic leukemia." (PMID 39802403, 2025). "Emerging studies have identified MDM2 as a key player in cancer metabolism, influencing glycolysis, oxidative stress responses, and mitochondrial function." (PMID 41170373, 2025). "These challenges have sparked interest in developing MdmX inhibitors and Mdm2/MdmX dual inhibitors to address the shortcomings of current Mdm2 inhibitors and improve therapeutic outcomes for related cancers." (PMID 40277907, 2025). "Mdm2 is normally expressed at low levels in cells but is overexpressed in cancer cells, thereby degrading large amounts of proteins." (PMID 40295432, 2025). "MDM2 is a critical oncogene extensively studied for its role in carcinogenesis, cancer prevention, and treatment." (PMID 40046748, 2025). "The clinical translation of MDM2 inhibitors illustrates both the promise and perils of targeting fundamental cancer pathways." (PMID 41170373, 2025).
cancer (continued). "MA exerts its anticancer effects by targeting key proteins such as EGFR, SRC, HSP90AA1, MDM2, and IGF1R, which are often overexpressed or mutated in resistant cancer cells." (PMID 40070571, 2025). "Nutlin-3a, which is undergoing clinical trials in cancer, is a well-characterized and highly specific inhibitor of MDM2." (PMID 39920118, 2025). "This difference leads to distinct cell fates and provides a therapeutic window that has important implications for the use of MDM2 inhibitors as potential cancer treatments." (PMID 39858058, 2025). "In this review, three oncogenic pathways, RAS, PNCA, and MDM2 are taken as examples in develop cancer targeted therapy using pan-cancer approaches, with key findings be applicable to specific cancer strategies." (PMID 41170373, 2025). "Murine double minute 2 (MDM2), an oncoprotein, was discovered by its increased expression in a spontaneously transformed mouse cancer cell line." (PMID 40308267, 2025). "Clinically, MDM2 is frequently dysregulated in various cancers, where its amplification or overexpression serves as a key oncogenic event." (PMID 41170373, 2025). "In pathological states (e.g., cancer), MDM2 is often overexpressed due to chromosomal amplification or mutations in various tumors (e.g., sarcomas, breast cancer, liver cancer, neuroblastoma)." (PMID 41300734, 2025). "Disrupting MDM2’s dimerization interface therefore offers an unparalleled mechanistic approach to inducing broad MDM2/MDMX neutralization in cancer." (PMID 40896364, 2025). "Further investigations revealed that NFATc1 simultaneously regulates both NADK and MDM2, which collectively promote metabolic reprogramming and cell cycle progression, thereby accelerating cancer cell proliferation." (PMID 41203626, 2025).
cancer (continued). "The cancer-specific elevation of RNA editing and the reduction of MDM2 levels upon ADAR1 silencing underscore the regulatory role of ADAR1-mediated 3’UTR editing." (PMID 40381037, 2025). "KRT-232 (MDM2 inhibitor inducing apoptosis) only tested in the second T-PLL cohort showed a similar effectivity to reduce the T-PLL cancer cell viability." (PMID 41146244, 2025). "Finally, an analysis stratified by family history of cancer revealed a differential distribution of MDM2 rs2279744 genotypes only among those with a family history of cancer (p = 0.0020), suggesting that the risk of the GG genotype of MDM2 rs2279744 is particularly relevant in this subgroup." (PMID 39857959, 2025). "MDM2-A, MDM2-B and MDM2-C are the most frequently detected and studied MDM2 protein isoforms in human cancer." (PMID 39960347, 2025). "While we have shown that Ezetimibe’s effectiveness is reduced in depleted Mdm2, it remains to be elucidated if the overexpression of Mdm2 is mandatory for the Ezetimibe-dependent killing of cancer cells." (PMID 39857778, 2025). "While the therapeutic rationale remains compelling, particularly for MDM2-amplified cancers, the narrow therapeutic window has prevented regulatory approval to date." (PMID 41170373, 2025). "In cancers that are non‐responsive to MDM2 degradation alone, WB156 acts as a GSPT1 degrader to induce anti‐proliferative effects." (PMID 41194439, 2025).
cancer (continued). "Among these drivers, RAS, PCNA, and MDM2 have become critical targets due to their roles in a broad-spectrum of cancer biology, e.g., cell proliferation, survival, and genomic stability." (PMID 41170373, 2025). "Clinically, this dysregulation is consistently associated with aggressive disease progression, therapy resistance, and poor patient outcomes, solidifying MDM2’s role as a critical pan-cancer biomarker and therapeutic target." (PMID 41170373, 2025). "A previous report indicated that the cardioprotective and anti-cancer activities of DMY against Dox depend on the interaction between MDM2 and its substrate proteins." (PMID 41226293, 2025). "To assess the interaction of potential inhibitors with MDM2, we surveyed infected cancer cell lines expressing MDM2 and those subsequently treated with Idasanutlin (identified via our previous analysis)." (PMID 40251828, 2025). "In cancer models, MDM2 depletion enhances osteoblastic differentiation and reduces the efficiency of induced pluripotent stem cell (iPSC) formation, further highlighting its role in stem cell maintenance." (PMID 41170373, 2025). "In this study, our results showed that inhibiting MDM2 can indeed attenuate the enhanced malignant phenotypes induced by ARID1A deficiency, including cancer progression and Osimertinib resistance." (PMID 39773749, 2025). "Idasanutlin, a specific MDM2 inhibitor, was studied to understand its transcriptional effects on well-characterized cancer cell lines, aiming to elucidate its mechanism of action." (PMID 40251828, 2025). "The results revealed significant differences in MDM2 serum levels among individuals with different MDM2 rs2279744 genotypes in both controls and cancer patients: serum MDM2 mRNA levels increased progressively with the number of variant G alleles." (PMID 39857959, 2025). "The genomic amplification of the MDM2 locus, located on chromosome 12q15 in humans, is a common alteration in most cancers." (PMID 40149342, 2025).